IL4R (interleukin 4 receptor)
Diseases named in the same sentence as IL4R in open-access papers (continued):
Sharing a sentence is not in itself a finding about the gene and the disease.
colitis (continued). "The disease activity index was calculated as the average of the diarrhea score and rectal bleeding score and was significantly attenuated in IL-4Rα-/- colitis mice compared with WT colitis mice (3.7 ± 0.2 in WT colitis, 1.1 ± 0.3 in IL-4Rα-/- colitis on day 7; p < 0.001)." (PMID 33192516, 2020). "Consistent with the transcriptome analysis result, the qPCR analysis results showed that the Nox1 mRNA expression in the colons of IL-4Rα-/- colitis mice was significantly higher than that in the colons of WT colitis mice (0.21 ± 0.04 in WT colitis, 2.00 ± 0.26 in IL-4Rα-/- colitis; p < 0.05)." (PMID 33192516, 2020). "Thus, we used an experimental colitis model to investigate the role of IL-4Rα in intestinal inflammation." (PMID 33192516, 2020). "In a recent study, rIL-33 induced Th2-type cytokines directly via IL-4 and IL-4R in colitis." (PMID 26161006, 2015). "However, the increase in Cxcl2 and Il-1β mRNA expression was significantly suppressed in the colons of IL-4Rα-/- colitis mice (Cxcl2; 5.3 ± 1.7 in WT colitis, 0.5 ± 0.3 in IL-4Rα-/- colitis; p < 0.05, Il-1β; 6.6 ± 2.1 in WT colitis, 0.3 ± 0.1 in IL-4Rα-/- colitis; p < 0.01)." (PMID 33192516, 2020). "For this reason, we sought direct evidence for a role for M2a Mφ in recovery from DSS-induced colitis by comparing the sensitivity of WT (BALB/c) and IL-4Rα−/− (on a BALB/c background) mice to DSS." (PMID 37768050, 2023). "Since IL-4Rα signaling was required for the repair of DSS-induced colitis, we next sought to determine if the worsened colitis of DSS-treated TLR4-SNP mice was attributable to a decreased capacity for differentiation of M2a Mφ." (PMID 37768050, 2023). "We extended our findings in the IL-4Rα−/− mice by showing that mice in which PPARγ had been deleted in myeloid cells (133, 147, –, 149) were also extremely sensitive to DSS-induced colitis." (PMID 37768050, 2023). "By using IL-4Rα−/− mice, our study has provided the first direct experimental evidence for the role of IL-4/13 signaling in the repair of DSS-induced colitis in WT mice." (PMID 37768050, 2023). "To investigate the role of IL-4Rα in the intestinal mucosal inflammation, we used a model of DSS-induced colitis." (PMID 33192516, 2020). "Mice lacking IL-4Rα did not develop disease in this model, further indicating a potential role for IL-4 in the development of colitis and inflammation." (PMID 34737752, 2021). "The production of ROS was significantly increased in the colons of IL-4Rα-/- normal mice compared with WT normal mice (0.7 × 108 ± 0.1 × 108 RLU/mg protein in WT normal, 9.8 × 108 ± 0.8 × 108 RLU/mg protein in IL-4Rα-/- colitis; p < 0.05)." (PMID 33192516, 2020). "We also observed significant increase in the production of ROS in the colons of IL-4Rα-/- colitis mice compared to WT colitis mice, (0.8 × 108 ± 0.1 × 108 RLU/mg protein in WT colitis, 10.3 × 108 ± 3.2 × 108 RLU/mg protein in IL-4Rα-/- colitis; p < 0.01)." (PMID 33192516, 2020).
liver fibrosis (9 papers, 2008 to 2024). "In that report, mice with tissue macrophage-specific deletion of IL-4Rα showed increased inflammation after Schistosoma mansoni infection but little change in their liver fibrosis status." (PMID 36016937, 2022). "In OB, interleukin-4 and interleukin-13 indicated via the IL-4R modulates adipose tissue lipolysis, insulin sensitivity, and liver fibrosis." (PMID 36314741, 2022). "Intriguingly, however, our findings also indicate that B cells mediate the down-regulation of hepatic fibrosis in this context independently from IL-4Rα expressing B cells." (PMID 30619289, 2018). "Moreover, M2 macrophages activation after Schistosoma infection induces the secretion of pro-fibrosis factor and promotes liver fibrosis through IL-4Rα/IL-13Rα1 signaling pathway." (PMID 39632841, 2024). "Interestingly, abrogation of IL‐4Rα signaling on CD11c+ cells resulted in smaller granulomas, reduced liver fibrosis, indicated by reduced hydroxyproline concentrations, and normal serum aspartate transaminase (AST) levels compared to infected IL‐4Rα−/lox littermate control mice." (PMID 30500088, 2019). "Thus, in contrast to the enhanced liver toxicity observed in IL-4−/−, IL-4Rα−/−, and LysMCreIL-4R−/− mice, CAT2−/− mice developed significant liver fibrosis, portal hypertension, and collateral vessels, which are features of severe hepatosplenic disease." (PMID 18369473, 2008). "Thus, alterations in non-hematopoietic IL-4Rα expression may impact hepatocellular damage, hepatic fibrosis, and adipocyte differentiation and function." (PMID 34302121, 2021).
Sepsis (9 papers, 2010 to 2025). Sepsis is defined as life-threatening organ dysfunction caused by a dysregulated host response to infection. "Strikingly, S. mansoni infection of IL-4Rα-deficient animals that lack most Th2 effector responses results in lethal sepsis once eggs produced in the mesenteric blood vessels cross the intestinal wall." (PMID 21589896, 2011). "Patients with higher risk scores tended to express lower levels of LTB4R, HLA-DMB and IL4R, indicating that upregulation of the three IRGs was a favorable prognostic factor in sepsis." (PMID 37033939, 2023). "We then analysed peritoneal macrophages from sepsis-surviving mice by flow cytometry and observed increased expression of IL-4Rα compared to that of the naive mice." (PMID 28374774, 2017). "A similar scenario plays out during infections with many gut nematodes, with broad-spectrum antibiotics providing at least partial protection from sepsis when IL-4Rα-driven barrier immunity is impaired." (PMID 21589896, 2011). "In our research, the result showed the upregulated IL4R expression in sepsis." (PMID 36860871, 2023). "However, the specific role and mechanism of IL4R in sepsis requires further elucidation." (PMID 36860871, 2023). "Similarly, IL-4R (+1902 A/G) polymorphism and mortality was observed, but it failed to correlate towards susceptibility for sepsis." (PMID 26561011, 2015). "Compared with healthy controls (n = 42), IL4R and LTB4R were significantly upregulated in sepsis patients (n = 479), while HLA-DMB was significantly downregulated (all P < 0.001)." (PMID 37033939, 2023). "The qPCR data exhibited the same pattern of expression of these genes as the GSE65682 dataset, with IL4R and LTB4R being expressed at significantly higher levels in sepsis cases and HLA-DMB exhibiting the opposite trend (all P < 0.01)." (PMID 37033939, 2023). "To clarify whether AAM were involved in the L. sigmodontis-mediated protection against an E. coli-induced sepsis, we used IL-4Rα/IL-5 double deficient BALB/c mice—which do not develop AAM, and IL-4-deficient BALB/c mice, which lack the suppressive effect of AAM." (PMID 25611587, 2015). "As iLckcreIl4ra−/lox mice did not develop gut injury or endotoxaemia, we concluded that IL-4Rα responsiveness by T cells is not essential for the control of intestine-derived sepsis." (PMID 20502521, 2010).
viral infection (9 papers, 2013 to 2026). "Once we performed our subgroup analyses, we found that selective JAKis were associated with increased risk of viral infections (OR: 2.60 [1.26–5.36]) as well as IL-4R targeted biologics (OR: 1.97 [1.07–3.61])." (PMID 41303888, 2025). "dupilumab, by competitively inhibiting IL-4 and IL-13 binding to IL-4Rα, attenuates Th2 cytokine-mediated enhancement of IL-8 production induced by dsRNA or viral infection in epithelial cells." (PMID 41576028, 2026). "The vIFN-γbp had minimal impact on CTL activity in WT, IL-4−/− and IL-4Rα−/− mice as these strains generated comparable responses to WT or mutant virus infection." (PMID 25751266, 2015). "Data indicate that the amount of IL-4 available during virus infection can regulate the expression of IL-4Rα on CD8+ T cells in a STAT6 dependent manner." (PMID 23383283, 2013). "Our results clearly indicated that amongst the different IL-4/IL-13 receptor components only cell surface IL-4Rα expression was significantly down-regulated on activated CD8+ T cells following virus infection." (PMID 23383283, 2013). "Interestingly, TCs in the ACR patients expressed high levels of IL-4, which was predicted to bind IL-4R and IL-2R in TC-MC interactions and was reported to enhance viral infection." (PMID 32780218, 2020). "In the second, the IL-4Rα−/− and IL-13−/−/IL-4Rα−/− mice exhibited increased susceptibility to WT virus infection but the absence of vIFN-γbp during infection mitigated the increased susceptibility." (PMID 25751266, 2015). "Thus, elevation of IL-4Rα expression on CD8+ T cells during virus infection strongly correlated with the reduction of anti-viral IFN-γ+ TNF-α+ CD8+ T cell responses." (PMID 23383283, 2013). "Thus, we propose that regulation of IL-4Rα expression during virus infection plays an important role in regulating the quality of anti-viral CD8+ T cell immunity." (PMID 23383283, 2013). "Therefore, down-regulation of cell surface IL-4Rα expression on activated CD8+ T cells is a general feature of virus infections in vivo." (PMID 23383283, 2013). "However, following virus infection only IL-4Rα was notably differentially regulated on certain immune cell subsets (i.e. CD4+ T cells, CD8+ T cells and DCs)." (PMID 23383283, 2013). "In addition, viral infection or dsRNA may enhance the expression of Th2 cytokines and the IL-4Rα complex." (PMID 41576028, 2026). "We determined using a murine model of allergic asthma whether these mice experienced increased morbidity from pandemic H1N1 (pH1N1) viral infection and whether blockade of interleukin-4 receptor α (IL-4Rα), a critical mediator of Th2 signalling, improved their outcomes." (PMID 33653328, 2021). "Markers of polymorphonuclear myeloid-derived suppressor cells (PMN-MDSCs), CEACAM8 (CD66B) and OLR1 (LOX-1), and markers of monocytic MDSCs (M-MDSCs), IL-4R, ITGAM (CD11B), including a functional marker of MDSCs, ARG1, were positively correlated with the severity of viral infection." (PMID 33765435, 2021). "Furthermore, this signaling mechanism also appears to be important in elevating IL-4Rα expression on naïve and effector CD8+ T cells in vivo following virus infection." (PMID 23383283, 2013). "Despite recent studies showing the importance of regulating IL-4Rα expression on CD4+ T cells following parasitic infection in vivo, only few studies have addressed how the cytokine receptors for IL-4/IL-13 are regulated on CD8+ T cells following virus infection in vivo." (PMID 23383283, 2013). "IL-4Rα mAb treatment did not significantly affect the expression of IFNβ, IFNλ1, or the cytosolic pattern recognition receptor MDA5 following T2 stimulation and viral infection." (PMID 40370530, 2025).
cutaneous leishmaniasis (8 papers, 2013 to 2021). Leishmaniasis affecting the skin. "In global abrogation of IL-4Rα, the progression of cutaneous leishmaniasis (caused by L. major and L. mexicana) is severely impaired resulting in protection from infection and eventually a healing outcome." (PMID 35154068, 2021). "We found that during experimental cutaneous leishmaniasis, KRT14cre IL-4Rα−/lox BALB/c mice were more susceptible to infection, similar to littermate control IL-4Rα−/lox BALB/c mice, following subcutaneous (s.c.)infection in the footpad or intradermal (i.d.)infection in the ear." (PMID 30275010, 2018). "In contrast, female CD11ccreIL-4Rα-/lox showed fulminant cutaneous leishmaniasis characterized by increasing footpad swelling similar to IL-4Rα-/lox littermate control BALB/c mice during the 8week period." (PMID 35154068, 2021). "Using this mouse strain, we showed that impairment of IL-4Rα signaling on DCs in BALB/c mice resulted in hypersusceptibility to cutaneous leishmaniasis." (PMID 29343807, 2018). "To test the role of IL-4 or IL-13 for the action of PSG during cutaneous leishmaniasis we co-infected WT and IL-4Rα-/- BALB/c mice with a low dose of L. mexicana metacyclics in the presence or absence of PSG." (PMID 29352310, 2018). "Infection of CD11ccreIL-4Rα-/lox mice with L. major LV39 and IL81 revealed IL-4Rα signaling on DCs to be highly important in protection against cutaneous Leishmaniasis." (PMID 24204259, 2013). "Accordingly, our previous study in CD11ccreIL-4Rα−/lox mice, which have impaired IL-4 receptor alpha (IL-4Rα) expression on CD11c+ cells including DCs, confirmed a protective role for IL-4/IL-13-responsive DCs in replication and dissemination of parasites during cutaneous leishmaniasis." (PMID 32039054, 2019). "KRT14cre IL-4Rα−/lox BALB/c mice remain susceptible to L. major infection, similar to littermate control IL-4Rα−/lox BALB/c mice, during experimental cutaneous leishmaniasis in the footpad." (PMID 30275010, 2018). "Conversely, during experimental cutaneous leishmaniasis in C57BL/6 mice with a global deletion of IL-4Rα, it was seen that the deletion had no impact on resistance in these mice." (PMID 30275010, 2018). "In contrast to the well characterized model system for cutaneous leishmaniasis not much is known about the impact of the IL-4Rα-Arg-1 axis on the course of experimental Chagas disease." (PMID 30555475, 2018). "The absence of IL-4Rα signalling on DCs therefore appears to have a more complex influence on the dendritic cells than just affecting IL-12 production during cutaneous Leishmaniasis in vivo." (PMID 24204259, 2013). "Furthermore, the development of type 2 antibody responses in non-healing cutaneous leishmaniasis occurs independently of IL-4Rα signaling on DCs." (PMID 35154068, 2021).
gastric cancer (8 papers, 2014 to 2024). A primary or metastatic malignant neoplasm involving the stomach. "For the Romanian population, the IL-4R −3223CÆT polymorphism has been shown to be associated with gastric cancer." (PMID 34484153, 2021). "The analysis of the gastric cancer sequencing data of TCGA showed that the expression of IL-4R was strongly correlated with the infiltration of macrophages." (PMID 39003253, 2024). "At the same time, IL-4 and IL-4R were highly expressed in tumor tissues, while in the public database, MSIscore and TMB in gastric cancer tissues were decreased with the increase of IL-4 and IL-4R expression." (PMID 39003253, 2024). "We found that among the 13 cell subsets isolated from gastric cancer tissues, IL-4R was mainly expressed in macrophages, monocytes, stromal cells and epithelial cells." (PMID 39003253, 2024). "IL-4R is expressed in human gastric cancer cell lines, such as CRL1739, and its expression contributes to local metastasis in colorectal cancer, making it an attractive target for CRC therapy." (PMID 37176567, 2023). "In addition, xCELL immunoinfiltration analysis was performed on the gastric cancer RNA-seq data of TCGA, and it was found that M2 macrophage infiltration increased and Th1 and Th2 cell infiltration decreased with the activation of IL-4/IL-4R axis." (PMID 39003253, 2024). "In addition, to further confirm the role of IL-4/IL-4R axis in gastric cancer, analysis of TCGA data showed that high expression of IL-4R was correlated with poor OS and PFS in patients with gastric cancer." (PMID 39003253, 2024).
atopic asthma (7 papers, 2009 to 2023). An asthma that is characterized by symptoms that are triggered by an allergic reaction caused by inhaled allergens such as dust mite allergen, pet dander, pollen and mold. "A single nucleotide polymorphism in the IL-13 cognate receptor, IL4Rα, based on meta-analysis, identified the Q551R (+1652 A/G, rs1801275) IL4R variant to impart a combined OR, 1.6; P = 0.004 for risk of atopic asthma." (PMID 23283176, 2011). "Evidence of the importance of induction of a Th2-biased response is of particular interest, as this is clearly of clinical relevance in childhood asthma and recent studies suggest that inhibition of IL-4Rα can reduce some of the clinical manifestations in patients with atopic asthma." (PMID 20122285, 2010). "For atopic asthma, many monoclonal antibodies were developed and showed potential effects: Omalizumab and Dupilumab are both monoclonal antibodies that bind to IgE and IL-4Rα respectively, and may be treatment options when atopic asthma is persistent and inadequately controlled by ICS." (PMID 37684679, 2023).
lung carcinoma (7 papers, 2013 to 2025). "Consistently, nuclear expression of IL4Rα and IL13Rα1 was presented in soft tissue sarcomas, clear cell renal cell carcinoma, squamous cell carcinoma, and lung cancer." (PMID 35207737, 2022). "In addition, the expression of IL4Rα and/or IL13Rα1 was observed in both the cytoplasm and nuclei of human cancer tissue samples, such as clear cell renal cell carcinoma, squamous cell carcinoma, and lung cancer." (PMID 33419470, 2021). "In addition, IL-4Rα blockade in the presence of IFNγ + TNFα significantly enhanced the autologous T-cell mediated cancer cell killing as measured by Annexin V positivity of EpCAM-expressing lung cancer cells and promoted the cancer cell elimination induced by PD-1 blockade." (PMID 40091029, 2025).
psoriasis (7 papers, 2018 to 2025). An autoimmune condition characterized by red, well-delineated plaques with silvery scales that are usually on the extensor surfaces and scalp. "Moreover, many molecularly targeted drugs for psoriasis and AD—TNF, IL-12/IL-23p40 subunit, IL-23p19 subunit, IL-17A, IL-17RA, and IL-4Rα—have been developed." (PMID 29642409, 2018).
skin inflammation (7 papers, 2014 to 2025). "The pathogenic importance of IL-4/IL-13 signaling in AD has been recently highlighted because its blockage by dupilumab, a specific anti-IL-4 receptor α (IL-4Rα, IL4R) antibody, successfully improves skin inflammation in patients with AD." (PMID 31284553, 2019). "Furthermore, a study in mice showed that deletion of IL4Rα sensitizes neurons to other pruritogens and that IL4Rα is required to elicit a chronic itch sensation in AD-like skin inflammation." (PMID 32664385, 2020). "Indeed, TLR2 activation together with IL-4R signaling transfers acute Th2-driven dermatitis (48 h before dermatitis resolution) into long-lasting skin inflammation (14 days) with enhanced expression of the Th1 cytokine IFN-γ." (PMID 26217343, 2015). "IL-13 and IL-4 share the same receptor subunit, the IL-4Rα chain, and IL-4Rα/IL-13Rα1 activates STAT6 via the JAK-STAT signaling cascade or tyrosine kinase 2, which in turn drives skin inflammation." (PMID 39629076, 2024).
airway hyperresponsiveness (6 papers, 2014 to 2025). "By utilizing IP deficient mouse lungs and PCLS models, we have demonstrated that immunoproteasome is a negative regulator of IL-4Rα expression and type 2 inflammation, as well as airway hyperresponsiveness." (PMID 40170850, 2025). "In the present study, we hypothesize that IP reduces lung IL-4Rα levels, leading to reduction in type 2 inflammation, a key contributor to airway hyperresponsiveness." (PMID 40170850, 2025). "They showed that airway hyperresponsiveness, remodeling and eosinophilic inflammation were not affected by decreased development of M2 macrophages by using LysMcre mice with macrophage-restricted IL-4 receptor-α (IL-4Rα)-deficiency." (PMID 29572536, 2018). "While we did not determine the precise mediators driving airway hyperresponsiveness in the absence of IL-4R signaling, we suspect that macrophage- and neutrophil-derived TNF-α plays a role." (PMID 24907978, 2014).
eczema (6 papers, 2012 to 2025). "Dupilumab (interleukin-4 receptor inhibitor) has been shown to be effective, especially in those with underlying eczema." (PMID 39171012, 2024). "Dupilumab, an anti-IL-4Rα antibody that blocks IL-4 and IL-13 signaling, was approved for treatment of moderate to severe eczema (AD) in the United States in 201725." (PMID 40312358, 2025).